KCNA1 (potassium voltage-gated channel subfamily A member 1)
Diseases named in the same sentence as KCNA1 in open-access papers (continued):
Sharing a sentence is not in itself a finding about the gene and the disease.
Myokymia (26 papers, 2008 to 2025). Myokymia consists of involuntary, fine, continuous, undulating contractions that spread across the affected striated muscle. "Mice with KCNA1 mutations display spontaneous EMG activity in the hindlimbs compatible with myokymia." (PMID 41008569, 2025). "Myokymia is the second most common, linked to 52% of KCNA1 variants and usually occurring in combination with EA1." (PMID 37240170, 2023). "Myokymia is a common manifestation of KCNA1 channelopathy, occurring in 52% of pathogenic or likely pathogenic KCNA1 variants and usually in combination with EA1 (82% of the time)." (PMID 37240170, 2023). "EA1 and myokymia, the most common diseases associated with KCNA1 variants, show relatively even mutation distributions across the various protein domains." (PMID 37240170, 2023). "Out of the 17 recently identified KCNA1 variants, eight display myokymia phenotypes, including two in the S2 domain affecting the same amino acid (A242T and A242S)." (PMID 37240170, 2023). "The myokymia-associated KCNA1 variants are present across most of the protein domains with the highest rates occurring in S2 (88%) and the S2–S3 linker (100%) regions." (PMID 37240170, 2023). "Finally, in some rare instances, KCNA1 mutations cause hypomagnesemia, paroxysmal dyskinesia, and myokymia." (PMID 32316562, 2020). "Potassium voltage-gated channel subfamily A member 1 (KCNA1) is a coding-gene and mutations in this gene have been linked to myokymia with periodic ataxia (AEMK) in humans." (PMID 36421827, 2022). "Interestingly, some patients with KCNA1 mutations also exhibit signs of PNH, such as myokymia or neuromyotonia, either isolated or combined with other phenotypes." (PMID 41008569, 2025). "KCNA1 is commonly associated with episodic ataxia 1 (EA1) but shows a broad phenotypic spectrum including myokymia and hypomagnesemia without EA1, developmental and epileptic encephalopathy, and neuromyotonia." (PMID 34305802, 2021). "Furthermore, a pure musculoskeletal phenotype lacking other KCNA1-related features has been described in a few individuals, displaying either isolated recurrent episodes of myokymia or myokymia associated with muscle hypertrophy and skeletal deformities." (PMID 33466780, 2021). "Myokymia (fine twitching or intermittent cramps and stiffness) is a persistent interictal feature, which is very suggestive of KCNA1 but is recognized in other EAs including EA3 (no known causative gene, linked to cytogenic region Chr1q42) and PxMD-UBR4 (previously called EA8)." (PMID 34177764, 2021).
channelopathy (17 papers, 2011 to 2026). Channelopathies are a group of diseases caused by the dysfunction of ion channel subunits or their interacting proteins. "Recent research has revealed new pathogenic gene variants in KCNA1 channelopathy, providing valuable insights into genotype–phenotype correlations." (PMID 37240170, 2023). "These new findings enhance our understanding of KCNA1 channelopathy and will advance personalized diagnosis and treatment for patients with KCNA1-linked disorders." (PMID 37240170, 2023). "In this review, we will describe how new pathogenic KCNA1 mutations are expanding our understanding of genotype–phenotype correlations associated with KCNA1 channelopathy." (PMID 37240170, 2023). "Understanding genotype–phenotype correlations for KCNA1 channelopathy is challenging because mutations can result in a variety of different diseases, which often occur in combination." (PMID 37240170, 2023). "Although not traditionally recognized, it is now becoming increasingly apparent that musculoskeletal abnormalities and nystagmus can also be features of KCNA1 channelopathy, occurring in 17% and 6% of KCNA1 mutations, respectively." (PMID 37240170, 2023). "Nystagmus is a rare feature of KCNA1 channelopathy occurring in 6% (4/65) of pathogenic KCNA1 variants." (PMID 37240170, 2023). "In this review, we examine 17 recently discovered pathogenic or likely pathogenic KCNA1 variants to gain new insights into the molecular genetic basis of KCNA1 channelopathy." (PMID 37240170, 2023). "Given the great phenotypic variability associated with KCNA1 channelopathy, how many disease-causing variants, both SNPs and CNVs, have been missed or overlooked in gene sequencing studies as a result of sampling bias?" (PMID 32316562, 2020). "It was identified as a channelopathy connected with mutations in KV1.1 gene (KCNA1 in chromosome 12p13)." (PMID 23409712, 2013). "Section "KCNA1 mutation" describes the observed changes for the KCNA1 mutation that causes a loss of function channelopathy on the Kv1.1 channel, whereas Section "CACNA1 A rocker and tottering mutations" explores the effects of the tottering and rocker mutations of the CACNA1A gene." (PMID 40526235, 2025). "This work provides mechanistic insight into neurocardiac communication and suggests that KCNA1 -linked human channelopathies may similarly impact sleep and cardiovascular health, offering a potential translational framework for age-related disorders." (PMID 40470189, 2025). "Additionally, recently identified variants reveal potential correlations between KCNA1-channelopathy and musculoskeletal abnormalities and nystagmus." (PMID 37240170, 2023). "An improved knowledge of patients’ genetic background, including the presence of common variants, protein–protein interactions and brain networks functioning will be necessary to better understand the molecular mechanisms underlying KCNA1 channelopathies and to support therapeutic decisions." (PMID 35897654, 2022). "The HBM-VNR model could also be used to predict the effects on neuronal firing and circuit behaviour following the introduction of a pharmacological agent or channelopathy as was showcased in Sections "KCNA1 mutation" and "CACNA1 A rocker and tottering mutations"." (PMID 40526235, 2025). "Moving forward, improved understanding of KCNA1 genotype–phenotype relationships at the molecular and electrophysiological levels in animal models and patients will enable more precise clinical diagnostic assessment and better therapeutic strategies for KCNA1 channelopathy." (PMID 32316562, 2020). "Studies in mouse models provide support for the ability of genetic modifiers to significantly alter the clinical presentation of KCNA1-related channelopathy." (PMID 37240170, 2023). "Genetic mutations in KCNA1, CACNA1A, CACNB4, SLC1A3, SCN8A, KCNMA1, and ATP1A3 genes that encode ion channels lend support to the channelopathy theory." (PMID 37008993, 2023).
channelopathy (continued). "This study also strengthens the beneficial effect of acetazolamide and sodium channel blockers in KCNA1 channelopathies." (PMID 35897654, 2022). "What are the relative contributions of genetic modifiers and environmental factors to the phenotypic heterogeneity seen with KCNA1 channelopathy?" (PMID 32316562, 2020). "Elucidation of the complex relationship between KCNA1 variants and disease will enable better diagnostic risk assessment and more personalized therapeutic strategies for KCNA1 channelopathy." (PMID 32316562, 2020). "In summary, KCNA1 channelopathy exhibits broad variability in clinical disease presentation that appears to be influenced by the location and nature of the mutated amino acid residue." (PMID 32316562, 2020). "Finally, the recently identified variants reveal new associations between KCNA1 mutations and musculoskeletal disease and nystagmus, thus expanding the known phenotypic spectrum of KCNA1 channelopathy." (PMID 37240170, 2023). "In summary, the new genetic discoveries in KCNA1 channelopathy deepen our understanding of the relationship between genotype and phenotype, promising to improve the clinical management of patients through more accurate diagnosis, prognosis, and targeted therapeutic interventions." (PMID 37240170, 2023). "The association of several of these new variants with musculoskeletal and nystagmus phenotypes indicates that these two conditions may be more prevalent in KCNA1 channelopathy than previously thought." (PMID 37240170, 2023). "In addition, the ability of partial deletion of Kcna1 to improve ASD phenotypes in Scn2a+/– suggests Kv1.1 subunits as a novel target for therapy in autism due to Scn2a channelopathy." (PMID 33484493, 2021). "In addition, insights from animal models of KCNA1 channelopathy were considered, as well as the possible influence of genetic modifiers on disease expressivity and severity." (PMID 32316562, 2020). "Finally, the role of genetic modifiers in KCNA1 channelopathy is discussed as another potential factor affecting genotype–phenotype relationships in patients." (PMID 32316562, 2020). "This percentage was increased by the discovery of four new mutations (E49Q, R86Q, P264LfsTer10, and T268K) that exhibit various musculoskeletal abnormalities, suggesting these types of deficits may be a more common feature of KCNA1 channelopathy than previously thought." (PMID 37240170, 2023). "However, as more patients are discovered with nystagmus due to KCNA1 channelopathy, a more reliable correlation between the genotype and the phenotype may be revealed." (PMID 37240170, 2023). "Additionally, the new variants include the first two gain-of-function mutations ever discovered for KCNA1, the first frameshift mutation, and the first mutations located in the cytoplasmic N-terminal domain, broadening the functional and molecular scope of KCNA1 channelopathy." (PMID 37240170, 2023).
breast carcinoma (10 papers, 2017 to 2025). "Previous research identified that KCNA1 was downregulated in several tumor types, and might be associated with the aggressiveness of breast cancer." (PMID 31354026, 2019). "The downregulation of KCNA1 (a voltage-gated potassium channel subfamily member) has been correlated with breast cancer aggressiveness, lending its stage-IV salience in our analysis." (PMID 41048341, 2025). "Another relevant cKv, KCNA1, favors oncogene-induced senescence and lower aggressiveness in breast cancer cells." (PMID 38132443, 2023). "A previous study revealed the tumor suppressive role of KCNA1, supported by its downregulated levels in breast cancer cells." (PMID 31354026, 2019). "KCNA1 expression was reduced in human cancers, and this decrease correlated with an increase in breast cancer aggressiveness." (PMID 30011966, 2018). "The study also identified 22 unique ion channels in the metastatic state, of which GRIK2, GJB3, KCNB2, KCNA1 and KCNK2 were previously reported in breast cancer metastasis." (PMID 35326596, 2022). "Ectopic expression of KCNA1 inhibits the RAS-induced transformation, which is related to decreased aggressiveness in breast cancer." (PMID 33456676, 2020). "Many studies have shown that potassium channels, including KCNN4, KCNA1, Kv11.1, KCNK9, KCNE1, and GIRK1 are involved in the regulation of malignant breast cancer transformation." (PMID 34195184, 2021).
Seizure (10 papers, 2007 to 2026). A seizure is an intermittent abnormality of nervous system physiology characterized by a transient occurrence of signs and/or symptoms due to abnormal excessive or synchronous neuronal activity in the brain. "One study has shown that a long-term exposure (2 weeks) to ketone bodies (5 mM β-hydroxybutyrate and 1 mM acetoacetate) reduces spontaneous epileptiform activity in hippocampal slices from Kcna1-knockout seizure models." (PMID 40109279, 2025). "Seizures in Kcna1−/− mice resemble those in well-characterized models of temporal lobe epilepsy known to involve limbic brain regions and spontaneous seizures result in enhanced cFos expression and neuronal death in the amygdala." (PMID 34312446, 2021). "Seizures and a reduced lifespan have also been described in Kcna1 null mice, in which the expression of the Kv1.1 subunit is abolished, as well as in Kcnab2 null mice, lacking the modulatory subunit beta 2, which co-distributes extensively with Kv1.1 and Kv1.2 in the adult rat brain." (PMID 17925011, 2007).
Epileptic encephalopathy (8 papers, 2015 to 2023). A condition in which epileptiform abnormalities are believed to contribute to the progressive disturbance in cerebral function. "Recent clinical findings in epileptic encephalopathy patients point to KCNA1 mutations being a potential molecular risk factor for ASD susceptibility." (PMID 33484493, 2021). "Epileptic encephalopathies (EEs) also arise from KCNA1 mutations which directly impact pore function." (PMID 32316562, 2020). "The presence of ASD‐like behaviors in both mice and an epileptic encephalopathy patient due to KCNA1 mutations suggests that KCNA1 may represent a new susceptibility gene for ASD phenotypes." (PMID 33484493, 2021). "Importantly, we here complement the phenotypes associated with variants in both prolines of the PVP motif that similar to KCNA1 are linked to severe early onset developmental and epileptic encephalopathy." (PMID 33802230, 2021). "The only other clinical case of KCNA1 epileptic encephalopathy was caused by a V368L mutation." (PMID 32316562, 2020). "Some patients with KCNA1 variants exhibit EA1 in combination with epilepsy, while others suffer from epilepsy or epileptic encephalopathy in the absence of EA1." (PMID 32316562, 2020).
temporal lobe epilepsy (7 papers, 2017 to 2024). A localization-related (focal) form of epilepsy characterized by recurrent seizures that arise from foci within the temporal lobe, most commonly from its mesial aspect. "We therefore asked if Kcna1-dCas9A treatment rescues behavioural deficits in our chronic intra-amygdala kainic acid model of temporal lobe epilepsy." (PMID 32129831, 2020). "We asked if Kcna1-dCas9A was able to rescue transcriptomic changes in the temporal lobe epilepsy model by performing RNAseq analysis on hippocampi from sham control animals injected with Ctrl-dCas9A and epileptic animals injected either with Ctrl-dCas9A or with Kcna1-dCas9A." (PMID 32129831, 2020). "Phenotypically, Kcna1−/− mice resemble well-characterized kainate-and kindling-induced seizure models of temporal lobe epilepsy (TLE), suggesting Kcna1 channel involvement in limbic brain circuits towards the generation and propagation of seizures." (PMID 34312446, 2021).
atrial fibrillation (6 papers, 2015 to 2025). A disorder characterized by an electrocardiographic finding of a supraventricular arrhythmia characterized by the replacement of consistent P waves by rapid oscillations or fibrillatory waves that vary in size, shape and timing and are accompanied by an irregular ventricular response. "When the hearts of Kcna1–/– mice were stimulated using intracardiac burst pacing, they exhibited increased susceptibility to atrial fibrillation (AF)." (PMID 31250689, 2019). "KCNA1 is a potassium channel massively expressed in neurons and its expression deregulation may facilitate the occurrence of atrial fibrillation." (PMID 26086673, 2015).
neuromyotonia (6 papers, 2020 to 2023). "Here, we have identified by whole-exome sequencing a novel de novo variant, T268K, in KCNA1 in a boy displaying recurrent episodes of neuromyotonia, muscle hypertrophy, and skeletal deformities." (PMID 33466780, 2021). "Here, we describe a novel variant in KCNA1 in a subject displaying muscle hypertrophy, neuromyotonia, and skeletal anomalies." (PMID 33466780, 2021). "Here, we report a new de novo missense variant (c.803C > A (p.Thr268Lys)) in the KCNA1 gene of a 9-year-old boy with a musculoskeletal phenotype characterized by rhabdomyolysis, lower limb stiffness, neuromyotonia, muscle hypertrophy, short stature, and skeletal deformities." (PMID 33466780, 2021). "The iterative characterization of channel defects at the molecular, network, and organismal levels contributed to elucidating the functional consequences of KCNA1 mutations and to demonstrate that ataxic attacks and neuromyotonia result from cerebellum and motor nerve alterations." (PMID 32331416, 2020).
Arrhythmia (5 papers, 2019 to 2025). Any cardiac rhythm other than the normal sinus rhythm. "In summary, this work discloses a functional role for Kv1.1 subunits in the ventricles for the first time by demonstrating that Kcna1 gene deletion in mice impairs both contractility and cardiac repolarization and alters arrhythmia susceptibility." (PMID 33427415, 2021). "Here, we investigated the heart-specific role of the Kcna1 gene, which encodes Kv1.1 voltage-gated potassium channel α-subunits expressed in both neurons and cardiomyocytes, where they shape action potential firing and influence seizure and arrhythmia susceptibility." (PMID 41239955, 2025).
Hypomagnesemia (5 papers, 2017 to 2021). An abnormally decreased magnesium concentration in the blood. "Two autosomal dominant KCNA1 mutations, N255D and L328V, have been linked to hypomagnesemia." (PMID 32316562, 2020). "Hypomagnesemia is not well represented among disorders caused by KCNA1 mutations, which complicates subsequent analysis of genotype–phenotype relationships." (PMID 32316562, 2020). "However, this theory does not explain why other KCNA1 mutations have not been reported to cause hypomagnesemia." (PMID 27234911, 2017). "Also, how does a voltage-gated K+-channel like KCNA1, which is closed and thus non-functional at normal apical membrane potential, cause hypomagnesemia in the first place?" (PMID 27234911, 2017).
cognitive deficits (4 papers, 2020 to 2023). "More recently, three de novo KCNA1 mutations have been described in four patients with infantile-onset drug-resistant seizures and cognitive impairment." (PMID 32331416, 2020).
Anxiety (3 papers, 2021 to 2024). Intense feelings of nervousness, tension, or panic often arise in response to interpersonal stresses. "Mice heterozygous for both Scn2a and Kcn1, a gene encoding for the pore-forming subunit of the voltage-gated potassium channel KV1.1(Scn2a+/−;Kcna1+/−), have reduced anxiety and autism-like behaviors compared to Scn2a+/− mice." (PMID 39606727, 2024).